VEGFA (vascular endothelial growth factor A)
Diseases named in the same sentence as VEGFA in open-access papers (continued):
Sharing a sentence is not in itself a finding about the gene and the disease.
colorectal cancer (continued). "Therefore, we elucidate a new regulatory mechanism of TPT1-AS1 in CRC angiogenesis and targeting the TPT1-AS1/NF90/VEGFA axis may provide a useful strategy for diagnosis and treatment for colorectal cancer patients." (PMID 32248186, 2020). "Moreover, it has been reported that VEGFA is overexpressed in 50% of colorectal cancers." (PMID 33585003, 2020). "While our study has elucidated the molecular mechanism by which POFUT2 promotes angiogenesis in colorectal cancer through the regulation of JUP and VEGFA, several limitations should be acknowledged." (PMID 41583504, 2026). "Lower panel: CHI3L1 leads to an increase in VEGF/VEGFA expression through the activation of the ERK1/2 and Akt pathways, promoting angiogenesis and tumor progression in colorectal cancer." (PMID 38177294, 2024). "Our further investigation revealed that CRC-EVs upregulate VEGFA by modulating the JAK/STAT3 pathway, thus promoting the angiogenesis of colorectal cancer tumors." (PMID 39596828, 2024). "IGF2BP2 and IGF2BP3 enhanced the stability of methylated ephrin type-A receptor 2 (EPHA2) and vascular endothelial growth factor A (VEGFA) mRNAs, respectively, in colorectal cancer cells." (PMID 38503745, 2024). "The production of VEGF and VEGFA, as well as the activation of the VEGF/VEGFR axis, have also been reported to be inhibited by EGCG in colorectal cancer cells." (PMID 36903395, 2023). "Meanwhile, in colorectal cancer, IL1R2 is involved in activating IL6, VEGFA, and MEK/ERK, promoting cell proliferation and metastasis, promoting tumor angiogenesis, and enhancing tumor drug resistance." (PMID 37728418, 2023). "IL-17A was shown to stimulate vascular endothelial growth factor A (VEGFA) production and promote angiogenesis in gastric and colorectal cancers." (PMID 37444399, 2023). "Database analysis revealed the expressions of VEGFA, CCND1, and YTHDF1 were all upregulated in colorectal cancer tissues compared with the normal cohort." (PMID 38001065, 2023). "We found that our highest-ranked predicted targets were significantly enriched in targets with FDA-approved therapeutics for colorectal cancer (p-value < 0.025) that included EGFR, VEGFA, and PTGS2." (PMID 37790614, 2023). "In colorectal cancer/melanoma, ALKBH5 accelerated expression of angiogenic genes, such as VEGFA and TGFβ1, which weakened the efficacy of GVAX/anti–PD-1 therapy." (PMID 36291060, 2022). "In colorectal cancer/melanoma, the ALKBH5 inhibitor ALK-04 downregulated expression of VEGFA and TGFβ1, thus inhibiting angiogenesis and enhancing efficacy of anti–PD-1 therapy." (PMID 36291060, 2022). "For instance, binding of Vascular Endothelial Growth Factor A (VEGF-A) to its receptor, VEGFR-2, represents a very relevant trigger for promoting angiogenesis and neovascularization in the context of colorectal cancer." (PMID 36428508, 2022). "Data from colorectal cancer cell lines, human endothelial cells and even zebrafish models have revealed that NFE2L2 downregulation results in VEGFA repression and consequently, angiogenesis inhibition." (PMID 35806488, 2022). "Sponge miR-126-5p promotes the expression of VEGFA, nasal mucus protein and TWIST, thereby promoting the metastasis of colorectal cancer." (PMID 34616746, 2021). "VEGF can produce different isoforms through mRNA splicing including VEGFA-165b, which is believed to be an anti-angiogenetic factor and downregulated in RCC, prostate cancer, colorectal cancer and melanoma." (PMID 34544400, 2021). "The circ001971/miR-29c-3p axis modulates colorectal cancer (CRC) growth, metastasis, and angiogenesis through VEGFA." (PMID 35069696, 2021). "Recent studies have demonstrated that PVT1 regulates the VEGFA/VEGF receptor 1 (VEGFR1)/AKT axis and promotes the tumorigenesis of colorectal cancer; the deletion of PVT1 can reduce tumor volume." (PMID 34336125, 2021).
colorectal cancer (continued). "Based on the 2020 TCGA data, the overexpression of HIF1α target genes VEGFA and SLC2A1 correlated with poor disease-free prognosis in colorectal cancer." (PMID 34686682, 2021). "Bevacizumab (Avastin, Roche) is a vascular endothelial growth factor A (VEGFA) monoclonal antibody, which inhibits tumor angiogenesis, and is widely used in colorectal cancer and lung adenocarcinoma." (PMID 31726490, 2020). "In colorectal cancer cells, lncRNA MALAT1 interacts with miR-126-5p in a ceRNA-depended mechanism to induce VEGFA expression and promote angiogenesis." (PMID 32993787, 2020). "Other AS events in various genes, such as VEGFA, APP, and NUMB, have been reported to regulate the development of colorectal cancer and have demonstrated potential as new targets for the diagnosis, prognosis, and treatment of this type of malignancy." (PMID 31443718, 2019). "Here, we showed that in clinically obtained colorectal carcinoma (CRC) specimens, Flt-1, the type 1 receptor for vascular endothelial growth factor A, was significantly upregulated." (PMID 29100318, 2017). "In colorectal cancer (CRC), PSG9 has been shown to promote angiogenesis through interaction with SMAD4, leading to enhanced nuclear retention of SMAD4 and activation of angiogenesis-related genes such as VEGFA and PDGF-AA." (PMID 40806565, 2025). "Additionally, in colorectal cancer, WTAP activates the MAPK signaling pathway by mediating m6A methylation in VEGFA mRNA via YTHDC1, promoting tumor progression." (PMID 40316995, 2025). "We validate our sensing platform by monitoring the secretion of vascular endothelial growth factor A (VEGF‐A), a protein critical in angiogenesis and tumor growth through the formation of new blood vessels, from colorectal cancer (CRC) cell line‐derived tumoroids." (PMID 38924371, 2024). "CCL5 recruits fibroblasts in colorectal cancer through CCR5-SLC25A24 signaling, which increases VEGFA and transdifferentiates fibroblasts into vascular endothelial cells, promoting tumor angiogenesis and collagen synthesis, ultimately promoting tumor development." (PMID 39835121, 2024). "While drugs targeting EGFR and VEGFA have been extensively studied for colorectal cancer, there are currently no reported drugs for this disease targeting CHI3L1." (PMID 38177294, 2024). "In addition to their previous study, the authors described four major profiles of colorectal cancers by their immune coordination (expression of CD3, CD8, granulysin, or IRF1) and angiogenesis (expression of vascular endothelial growth factor A [VEGF-A])." (PMID 35806328, 2022). "The VEGFA/VEGFR2/PI3K/Akt/Akt signal transduction method by VEGFRs was used to measure the VEGFA/VEGFR2/PI3K/Akt signal transduction pathway, thereby revealing the mechanism of 2′-FL on colorectal cancer." (PMID 36364081, 2022). "Vascular endothelial growth factor (VEGFA) and its receptors 1 fms-related tyrosine kinase 1 (FLT1) and kinase insert domain receptor (KDR) have been newly recognized as critical regulators of angiogenesis and inflammation in colorectal cancer." (PMID 31383782, 2019). "Supporting this, in DLD1 and HCT116 human colorectal carcinoma, recruited human patrolling monocytes in tumors secrete matrix metalloproteinase 9 (MMP9), a proteolytic enzyme fostering angiogenesis, triggering a release of matrix-bound VEGFA." (PMID 31474975, 2019). "Here we show that in normoxic colorectal cancer cells, E2 can repress HIF1-α and VEGFA expression." (PMID 29137421, 2017). "In this study, we have demonstrated that exosomal miR-320d derived from colorectal cancer cells enhances angiogenesis in vascular endothelial cells and promotes cancer cell metastasis by downregulating GNAI1 expression, enhancing JAK2/STAT3 protein phosphorylation, and increasing VEGFA expression." (PMID 39695099, 2024).
colorectal cancer (continued). "Furthermore, animal models have demonstrated that IGFBP-4 can increase VEGF-induced angiogenesis and that the m6A binding protein METTL3 can target VEGFA via IGFBP-2, encouraging the creation of colorectal cancer vasculogenic mimicry via the PI3K/AKT/mTOR and ERK1/2 signaling pathways." (PMID 38020199, 2023). "Moreover, in colorectal cancer, miR-150-5p inhibits tumor progression by targeting VEGFA; members of the STAT proteins, STAT1, STAT3, and STAT5, have been attested as regulators mediating the expression of VEGFA, involving the mechanisms of angiogenesis as well." (PMID 38737443, 2024).
melanoma (777 papers, 1997 to 2026). A malignant, usually aggressive tumor composed of atypical, neoplastic melanocytes. "To search for mechanisms underlying the CCL20/TNF/VEGFA secretory TAM phenotype associated with aggressive primary melanomas, and due to limited access to patient TAMs, we prepared tumor-conditioned macrophages." (PMID 34439098, 2021). "Rather than the number, size, or location of TAM, quantitative assessment of CCL20, TNF, and VEGFA cytokine content was associated with strong prognostic significance in primary melanoma." (PMID 34439098, 2021). "The current study identifies other angiogenic stimulators than VEGFA that are associated with vascular function and the development of hypoxia in microscopic melanoma xenografts." (PMID 29183378, 2017). "Melanoma progression is greatly favoured by angiogenesis and appears to be associated with an increase of vascular endothelial growth factor-A (VEGF-A) expression by tumour cells." (PMID 28977999, 2017). "Although most cancers show high expression levels of VEGF, in some cancers such as benign forms of melanoma and in cancers with high microsatellite instability lower expression of VEGFA are associated with better prognosis." (PMID 24688641, 2012). "Furthermore, high serum levels of VEGFA were associated with decreased overall survival in advanced melanomas, while low plasmatic VEGFA characterized patients responding to immunotherapy." (PMID 37183363, 2023). "To investigate whether oncogenic BRAF targeting associated with VEGFA removal similarly modulate the adaptive immunity in D4M melanomas, we analyzed by flow cytometry the number of tumors infiltrating T cells after 12 days of treatment." (PMID 37183363, 2023). "Similarly, angiogenic switch is involved in the outgrowth of melanoma and lung carcinoma in the brain and is linked to the upregulation of vascular endothelial growth factor A (VEGF-A)." (PMID 35737114, 2022). "Furthermore, previous studies have linked VEGFA to angiogenesis, while high levels in particular have been linked to poor OS in patients with melanoma who received ipilimumab therapy." (PMID 35836254, 2022). "Importantly, the high content of CCL20/TNF/VEGFA is strongly associated with a worse prognosis in primary melanoma patients." (PMID 34439098, 2021). "Several factors have already been implicated in peritumoral edema in other cancers, such as vascular endothelial growth factor-A, aquaporin-4, and metalloproteinases, but further study is needed to identify the critical edema mediators in melanoma and to understand how they are affected by CPIs." (PMID 31362777, 2019). "Here, we sought to test the hypothesis that the antitumor efficacy induced by the combinatorial use of BRAFi and VEGFA removal, BRAF/VEGFA targeting, correlates with the ability to induce an immune‐stimulatory milieu in a mouse syngeneic melanoma tumor model, derived from BRAF mutated murine cells." (PMID 37183363, 2023). "Our qPCR results showed that supernatants from the drug-treated groups significantly downregulated VEGFA and HIF-1α expression, thereby exacerbating the deficiency of oxygen and nutrients within the melanoma." (PMID 41596235, 2026). "Overexpression of JUP in melanoma has been shown to upregulate VEGFA expression, and tumors with elevated JUP display a larger area of CD31-positive staining, indicating increased angiogenesis." (PMID 41583504, 2026). "We believe that our findings support a rationale for clinical trials testing anti-angiogenic agents (e.g., Bevacizumab) in combination with anti-PD1 therapy (e.g., Pembrolizumab) in VEGFA-high melanoma patients." (PMID 40943183, 2025). "MOF-based hydrogel has also been used to treat melanoma by regulating melanoma prognostic markers (VEGFa and S100A6)." (PMID 39852047, 2025). "VEGFA (vascular endothelial growth factor A) plays a crucial role in melanoma progression through its involvement in angiogenesis, immune evasion, and metastasis promotion." (PMID 41168392, 2025).
melanoma (continued). "VEGFA secreted by malignant B16F10 melanoma cells vary from picogram to nanogram levels dependent on culture conditions." (PMID 38148112, 2024). "Growth and angiogenic factors: angiopoietin-2, endoglin, fibroblast activation protein (FAP), melanoma inhibitory activity, and vascular endothelial growth factor-A (VEGF-A) were significantly (p < 0.0001) elevated in EC patients." (PMID 39511039, 2024). "This offers potential for a new treatment strategy based on targeting VEGFA that aims to overcome resistance to BRAF blockade in melanoma." (PMID 37183363, 2023). "In this work, we explored the strategy of VEGFA/BRAF inhibition in immunocompetent melanoma murine models." (PMID 37183363, 2023). "Combinatorial BRAFi and VEGFA removal reshapes the TME maximizing the anticancer effects of ICB therapies, suggesting that VEGFA neutralization represents a further option to improve targeted therapy and immunotherapy in melanoma." (PMID 37183363, 2023). "In BRAF mutant D4M melanoma tumors, VEGFA/BRAF targeting reshaped the tumor microenvironment, largely by stimulating infiltration of M1 macrophages and CD8+ T cells, and sensitized tumors to immune checkpoint blockade (ICB)." (PMID 37183363, 2023). "Our study contributes to understanding the tumor biology of BRAFV600E melanoma and suggests VEGFA as therapeutic target." (PMID 37183363, 2023). "Our data suggest that VEGFA/BRAF targeting in melanoma induces the activation of innate and adaptive immunity and prepares tumors for ICB." (PMID 37183363, 2023). "Previously, we reported that bevacizumab, the anti‐human VEGFA monoclonal antibody (anti‐hVEGFA), delayed the onset of acquired resistance to BRAFi in a human melanoma tumor model developed in immunodeficient mice." (PMID 37183363, 2023). "Our studies in melanoma tumors suggested that BRAF/VEGFA targeting reshaped the TME, leading to an improvement of anti‐PD‐1 effectiveness and inducing an immunologic memory response able to reject a second tumor." (PMID 37183363, 2023). "In melanoma, improvements in overall survival by a single agent targeting VEGFA have historically been limited." (PMID 35577211, 2022). "Tumour-derived exosomes released by melanoma cells are loaded by pro-angiogenic factors, such as VEGFA and MMPs." (PMID 36077754, 2022). "We had previously identified the expression of CCL20/TNF/VEGFA cytokines by TAMs in a pilot study with cryopreserved human melanoma tissues." (PMID 34439098, 2021). "First, we established conditions to quantify by multicolor fluorescent-microscopy the content of CCL20, TNF, and VEGFA in CD68+ cells in FFPE melanoma tissues." (PMID 34439098, 2021). "Taken together, our data demonstrates that MIR205HG knockdown inhibits melanoma growth and progression by suppressing VEGFA expression and EMT via miR-299-3p." (PMID 33535182, 2021). "In this study, we investigated the role of MIR205HG/miR-299-3p/VEGFA axis in melanoma growth and progression." (PMID 33535182, 2021). "Vascular endothelial growth factor A (VEGFA) plays an important role in the growth, progression, and angiogenesis in several cancers including melanomas." (PMID 33535182, 2021). "MMP-2 upregulates vascular endothelial growth factor-A (VEGF-A) secretion by the tumor cells in human melanoma leading to the interaction of the melanoma cells with the lining of the blood vessels and favoring their extravasation." (PMID 34912809, 2021). "MIR205HG-silenced melanoma cells showed increased miR-299-3p expression and lower levels of both VEGFA mRNA and protein." (PMID 33535182, 2021). "In summary, our study demonstrates that silencing MIR205HG suppresses melanoma growth and progression by inhibiting the VEGFA expression and EMT via miR-299-3p." (PMID 33535182, 2021). "Accordingly, IL-8 induced VEGFA angiogenic activity and increased the aggressiveness of malignant melanoma cells." (PMID 33466236, 2021).